TGM5 (transglutaminase 5)
Description:
Catalyzes the cross-linking of proteins and the conjugation of polyamines to proteins. Contributes to the formation of the cornified cell envelope of keratinocytes.
Synonyms: TG(X); TGX; TGMX; PSS2; TGASE5; TGASEX
Tractability: Antibody: its Gene Ontology location is reachable by antibodies, with high confidence.
Gene: Protein-coding gene on chromosome 15 (43,232,590 to 43,266,928, reverse strand). Ensembl gene ENSG00000104055.
Subcellular location: Cytoplasm
Pathways (Reactome):
Developmental Biology: Formation of the cornified envelope
Gene Ontology:
Molecular function: protein binding; protein-glutamine gamma-glutamyltransferase activity
Biological process: epidermis development; peptide cross-linking; protein modification process
Cellular component: plasma membrane; cytoplasm
Genetic constraint (gnomAD): Loss-of-function variants: 68 observed, 80.44 expected, observed/expected ratio (o/e) 0.85, 90% interval 0.69 to 1.03. The upper end of that interval is the gene's LOEUF score, 1.03, which puts it in group 4 of 6, group 1 being the genes least tolerant of losing a copy. Missense variants: 841 observed, 941.28 expected, observed/expected ratio (o/e) 0.89, 90% interval 0.84 to 0.95. Synonymous variants: 346 observed, 371.35 expected, observed/expected ratio (o/e) 0.93, 90% interval 0.85 to 1.02.
Homologues: Orthologues: chimpanzee TGM5 (99% identical), macaque TGM5 (91% identical), pig TGM5 (86% identical), dog TGM5 (85% identical), guinea pig TGM5 (85% identical), rat Tgm5 (84% identical), rabbit TGM5 (84% identical), mouse Tgm5 (83% identical), zebrafish tgm5l (33% identical), zebrafish tgm8 (17% identical). Paralogues in human: TGM7 (49% identical), TGM6 (46% identical), TGM3 (43% identical), TGM2 (39% identical), TGM1 (34% identical), F13A1 (33% identical), EPB42 (31% identical), TGM4 (31% identical).
Diseases named in the same sentence as TGM5 in open-access papers:
TGM5 is named in the same sentence as 17 diseases in open-access papers, as found by Europe PMC text mining. Sharing a sentence is not in itself a finding about the gene and the disease. The quoted sentences say what the papers report.
peeling skin syndrome (6 papers, 2018 to 2025). Peeling skin syndrome (PSS) refers to a group of rare autosomal recessive forms of ichthyosis that is characterized clinically by superficial, asymptomatic, spontaneous peeling of the skin and histologically by a shedding of the outer layers of the epidermis. "Previous studies have demonstrated the role of TGM1 as a biomarker for psoriasis and the involvement of TGM5 in the pathogenesis of peeling skin syndrome." (PMID 41380997, 2025). "Transglutaminase 5 is widely expressed in the epidermis and the loss-of-function mutations of TGM5 result in skin peeling syndrome in humans." (PMID 30545030, 2018).
acral peeling skin syndrome (4 papers, 2012 to 2020). Acral peeling skin syndrome (PSS) is a form of PSS characterized by superficial peeling of the skin predominantly affecting the dorsa of the hands and feet. "It should be noted however, that another skin disorder, acral peeling skin syndrome (APSS, caused by mutations in TGM5), has only recently been classified as another subtype of EBS." (PMID 26432462, 2016).
ichthyosis (2 papers, 2008 to 2020). Disorders of cornification that are characterized by visible scaling and/or hyperkeratosis of most or all of the skin. "Interestingly, the same loss-of-function mutation in TGM1 and TGM5 have been shown to cause lamellar ichthyosis, a disease characterized by excessive scaling and shedding of the outer epidermis, and peeling skin syndrome, respectively." (PMID 19107207, 2008).
gastric cancer (1 paper, 2020). A primary or metastatic malignant neoplasm involving the stomach. "In contrast, other transglutaminases including TGM1, TGM4, TGM5, TGM6, and TGM7 exhibited a significant decrease in gene expression in the gastric cancer tissue samples." (PMID 32467608, 2020).
lung carcinoma (1 paper, 2023). "Previous genome-wide association studies suggest that rs748404, located at promoter of TGM5 (transglutaminase 5), is associated with lung carcinoma." (PMID 37058478, 2023). "Since rs748404 is located at the promoter region of TGM5 (transglutaminase 5), it is suggested that rs748404 might be associated with lung carcinoma by regulating TGM5 expression." (PMID 37058478, 2023).
pulmonary fibrosis (1 paper, 2020). Chronic progressive interstitial lung disorder characterized by the replacement of the lung tissue by connective tissue, leading to progressive dyspnea, respiratory failure, or right heart failure. "Concordantly, the genes encoding transglutaminases (TGM1, TGM2 and TGM5), which are enzymes responsible for crosslinking and also involved in pulmonary fibrosis, were significantly upregulated." (PMID 32698440, 2020).
TGM5 also shares sentences with these, for which no sentence is quoted: epidermolysis bullosa (2 papers); psoriasis (2); skin disorder (2); autosomal recessive congenital ichthyosis (1); bleeding disorder (1); genodermatosis (1); Huntington disease (1); hypotrichosis (1); infection (1); lamellar ichthyosis (1); spinocerebellar ataxia (1).